CXCR1 (C-X-C motif chemokine receptor 1)
Diseases named in the same sentence as CXCR1 in open-access papers (continued):
Sharing a sentence is not in itself a finding about the gene and the disease.
tumor (continued). "Consistently, patients with TNBC treated with chemotherapeutic drugs exhibited very poor survival rate and shorter disease-free survival time if their tumor samples expressed high levels of IL8, CXCR1/2 and Wnt signals." (PMID 28703802, 2017). "The up-regulation of the IL-8 receptors CXCR1 and CXCR2 is a frequent occurrence in human cancer and has been related to tumor progression." (PMID 28415590, 2017). "This suggests that CXCR1 and CXCR2 signaling provides the surviving re-grown tumor cells with a paracrine loop from IL-8 and CXCL-1 to maintain tumor cell survival." (PMID 27379204, 2016). "Several genes were up‐regulated in tumor tissues during the progression period, including CXCL1, CXCL2, CXCL3, and IL‐1β, while CXCR1 expression was down‐regulated." (PMID 27682863, 2016). "CXCR1+ cells were abundant in the stroma of control-sh-RM1 tumours, while in CXCL1-sh-RM1 tumours they were sparse." (PMID 27241286, 2016). "In addition, expression of p-p38, CXCR1 and mesenchymal fibronectin were markedly reduced in A549 erlotinib-resistant tumor cells pre-treated with the p38 kinase inhibitor, suggesting that blockade of p38 could alleviate mesenchymal features that, in turn, may contribute to tumor resistance." (PMID 27248176, 2016). "Acquisition of IL-8 and/or its receptors CXCR1 and CXCR2 are known to be a relatively common occurrence during tumor progression." (PMID 27348007, 2016). "Thus, down‐regulation of CXCR1 may favor tumor progression in mouse models of HCC." (PMID 27682863, 2016). "Several studies have supported that the function of CXCR1 and CXCR2 in tumor angiogenesis and of these two receptors, CXCR2 is the receptor most likely involved in IL-8 promoted angiogenesis in endothelial cells." (PMID 26559818, 2015). "IL-8 overexpression increases CXCR1 and CXCR2 expression on tumor cells, endothelial cells, and immune related cells (neutrophils and macrophages) resident in tumor tissue." (PMID 26504364, 2015). "CXCR1 and CXCR2 together with cognate chemokines are significantly upregulated in a number of cancers, where they act as key regulators of tumor cell proliferation, metastasis, and angiogenesis." (PMID 26087179, 2015). "IL-8 activates the CXCR1 and CXCR2 CK receptors of neutrophils implicating them in development and promotion of tumor progression and numerous inflammatory disorders." (PMID 25878893, 2015). "CXCR1 and CXCR2, receptors for IL-8, are highly expressed in tumor and endothelial cells and potentially mediate the angiogenic function of IL-8 in tumor angiogenesis." (PMID 26559818, 2015). "CXCR1/2 expressed by vascular ECs and CXCL8, the ligand produced by tumor and stromal cells, are known to promote angiogenesis through inducing EC migration and formation of tubules." (PMID 25110692, 2014). "CXCR2 expression is increased in some tumor types and pharmacological inhibition of CXCR1 and CXCR2 inhibits neutrophil recruitment into A547 lung tumor spheroids resulting in slower tumor growth." (PMID 25372289, 2014). "We report an increased expression of CXCL1, CXCR1 and CXCR2 in tumour, compared with the surrounding normal epithelium, providing evidence for enhanced autocrine CXC chemokine signalling in these cancer cells." (PMID 21285972, 2011). "Intermediate to strong expression of CXCL1, CXCR1 and CXCR2 was concurrently detected in the epithelium of stage II and stage III CRC tumours." (PMID 21285972, 2011). "We used immunohistochemistry to identify cells expressing CXCR1, CXCR2, CXCR3, CXCR4, CXCR5 and CCR1 in the tumour islets and stroma in 20 patients with surgically resected NSCLC." (PMID 20429924, 2010). "Sustained expression of CXCR1 and CXCR2 in tumour tissues was confirmed by immunohistochemical staining (data not shown)." (PMID 19401689, 2009). "Furthermore, IL-8 interacts with its cognate receptors CXCR1 and CXCR2 to promote tumor cell survival and induce epithelial–mesenchymal transition (EMT)." (PMID 41515435, 2025).
tumor (continued). "Notably, members of the CXC chemokine family, including CXCL1, CXCL2, CXCL3, CXCL5 and CXCL8, function through the activation of CXCR1 and CXCR2, playing a key role in promoting tumour angiogenesis." (PMID 39161078, 2025). "G31P is a synthetic form of CXCL8 with modifications in lysine to arginine (K11R) and glycine to proline (G31P) substitutions, which confer potent CXCR1/2 antagonism, thereby blocking ELR+ CXC chemokines signaling pathways involved in tumor growth, neutrophil infiltration, and resistance to therapy." (PMID 41425704, 2025). "CXCL6 functions through the CXCR1/2‐JAK‐STAT/PI3K axis and reshaping tumor lipid metabolism." (PMID 40305734, 2025). "Interestingly, CRC can produce CXCL8 themselves and increase the levels of CXCR1 and CXCR2, which helps the tumor grow, spread, and form metastases." (PMID 40943634, 2025). "Other CXCR inhibitors, such as CXCR1 and CXCR2 antagonists like SCH527123, have demonstrated efficacy in preclinical models of various cancers, highlighting their potential in modulating the tumor microenvironment and reducing metastasis." (PMID 41024311, 2025). "Similarly, inhibitors of chemokine receptors such as CXCR1/2 and CCR2/5 are being investigated as potential anti-cancer agents, with the aim of disrupting tumor-promoting inflammatory responses and inhibiting metastasis." (PMID 41180630, 2025). "Lastly, the inhibition of CXCR1/2 has been reported to sensitize cancer cells to docetaxel, while also modifying the immune microenvironment in HPV-negative HNSCC, thus promoting anti-tumor immunity." (PMID 40760079, 2025). "CXCR1/2 mRNA was found to be expressed in normal epithelial cells, CK positive tumor cells, and CK negative cells in the TME." (PMID 39639338, 2024). "Furthermore, an intriguing observation in multi‐primary tumours was the enhanced interaction between CXCL2/3/5/8 in macrophages and CXCR1/2 in neutrophils that has been previously reported to play critical roles in forming NETs in human neutrophils." (PMID 39601163, 2024). "Reparixin, CXCR1/2 inhibitor, significantly reduces TNBC tumor growth and metastasis." (PMID 38393465, 2024). "Thus inflammatory precursors from PBMC expressing CXCR1, CXCR3 and CX3CR1 selectively enter inflamed tumor tissues." (PMID 38390333, 2024). "Engineering CAR T-cells to coexpress chemokine receptors, such as CXCR1 or CXCR2 for IL-8-secreting ovarian or pancreatic tumors, may be an additional strategy to direct cells to the tumor and mitigate on-target/off-tumor toxicity in other tissues." (PMID 39674824, 2024). "Expression and localization of IL-8, CXCR1, and CXCR2 in normal tissues and HNSCC tumors were evaluated with a commercially available tissue array containing 70 tumor cases of unknown HPV status and 10 normal tissues." (PMID 39639338, 2024). "CRIP1 expressed in tumor cells promotes the infiltration of MDSCs via CXCL1/5-CXCR1/2 signaling, and the inhibition of CXCR1/2 decreases the recruitment of MDSCs and enhances the antitumor effect of PD-L1 treatment to improve resistance to immune-checkpoint blockers(ICBs)." (PMID 38982491, 2024). "Similarly, modification of the chemokine receptors CXCR1/CXCR2/CXCR5 to the surface of CAR-T cells can increase cellular transport within the tumor and anti-tumor efficacy." (PMID 38911868, 2024). "IL-8, a key pro-inflammatory chemokine, signals through two G protein-coupled receptors (GPCRs), CXCR1 and CXCR2, and has been shown to be upregulated in PCa and other cancers, including breast, lung, and pancreatic, promoting tumour cell proliferation and migration." (PMID 39199570, 2024). "Many agents targeting IL-8 and IL-8 receptors, and many combined strategies are under clinical investigation: monoclonal antibodies, neutralizing antibodies, direct antagonists, antibodies anti-CXCR1 and -CXCR2, in different tumor types, with the aim of increasing the anti-tumoral efficacy." (PMID 38443899, 2024).
tumor (continued). "Clusters of tumor cells positive for IL-8 mRNA were observed, while the expression of CXCR1/2 mRNA was homogeneously distributed across CD45 negative cells in the tumor." (PMID 39639338, 2024). "However, due to the higher expression of CXCR1 relative to CXCR2, CXCL8/IL-8 is more significant in this tumor’s development and function." (PMID 38673949, 2024). "While MOC1 tumor cells did not express high levels of CXCR1/2, we did observe a population of CXCR2+CD11b+Ly6G+ myeloid cells in the spleens and tumors of these mice which have been shown to be highly immune suppressive." (PMID 39639338, 2024). "Furthermore, by binding to its receptors CXCR1/CXCR2, tumor-derived IL-8 recruits neutrophils (PMNs) and myeloid-derived suppressor cells (MDSCs), which play critical roles in tumorigenesis." (PMID 39123403, 2024). "While our studies with xenograft models in vitro and in vivo detailed the sensitizing effect of CXCR1/2 inhibition to docetaxel efficacy on tumor cells directly, these models did not allow the interrogation of the effect of these agents on the immune system." (PMID 39639338, 2024). "After resistance, CXCR1+ neutrophils communicated more effectively with tumor cells, regardless of the direction of the signaling." (PMID 39638994, 2024). "Furthermore, VEGFA, KDR, CXCR1 and CXCR2 were significantly upregulated in tumour samples compared with paired normal samples, except for VEGFB, whose expression was not statistically significant." (PMID 38426619, 2024). "Additionally, CXCL8 can be involved in the proliferation, self-renewal, and recruitment of CXCR1/CXCR2-expressing cancer stem cells, which are known to promote tumorigenesis, tumor maintenance, metastasis, and drug resistance in many different cancers." (PMID 36725964, 2023). "Then, we investigated whether the TC microenvironment could recruit mast cells to the tumor stroma by chemotaxis by screening the chemokine receptors involved in mast cell migration, including CCR2, CCR5, CXCR1, CXCR2, CXCR4, and CXCR7." (PMID 37042867, 2023). "The percentage of elevated concentrations (diagnostic sensitivity) of CXCL1 (57%) and CXCR1 (61%) was higher than that of the classical tumor marker CEA (46%), but lower than that of CRP (76%), whereas it increased in the combined analysis of CXCL1 and CXCR1 with CEA or CRP." (PMID 37509572, 2023). "Chemokines secreted by TAMs, including CCL3, CCL5, CCL15, CCL18, CXCL8 and CXCL12, promote tumor metastasis, angiogenesis, cancer cell survival, immunosuppression and resistance of cancer cells after chemotherapy via CCR1/5, CCR5, CCR1, CCR8, CXCR1/CXCR2, CXCR4, respectively." (PMID 36173487, 2023). "As previously reported, tumor-generated IL-8 can attract M-MDSCs and G-MDSC (granulocytic-MDSC) from peripheral blood via CXCR1 and CXCR2, thus facilitating the extrusion of NETs, which can be blocked by the specific CXCR1/2 inhibitor reparixin." (PMID 38023616, 2023). "Thus, researchers have generated a CAR-T cell strategy capable of expressing IL-8 receptors (CXCR1 or CXCR2) thereby enhancing their capacity of infiltrating solid tumors, consequently exerting an anti-tumor effect." (PMID 36717905, 2023). "Therefore, emerging research suggests that combination therapies of monoclonal anti-CXCL8 antibodies or CXCR1/CXCR2 antagonists with standard anti-tumor (immuno)therapy can tackle the tumor immune escape and provide further benefit in anti-tumor treatment." (PMID 36725964, 2023). "On the one hand, myeloid-derived suppressor cells (MDSCs) can produce NETs under the stimulation of IL-8, and at the same time, in the tumor microenvironment, MDSCs can produce chemokines such as CXC chemokine receptor 1(CXCR1) and CXCR2 agonists to promote the production of NETs." (PMID 37373412, 2023). "Further potential avenues proposed to block protumor effects of TANs could be achieved by targeting the CXCL-8/CXCR-1/CXCR-2 axis, or targeting substances produced by TANS which promote tumor growth." (PMID 37143649, 2023).
tumor (continued). "Administration of IL-8 antibodies via SX-682 (a small molecule inhibitor targeting CXCR1 and CXCR2) reduces the number of immunosuppressive myeloid-derived suppressor cells (MDSCs) within the tumor microenvironment and enhances the efficacy of adoptive cell therapy with NK cells." (PMID 37143649, 2023). "If we could examine the downstream effect of CXCR1 compared to CXCR2 when bound to CXCL8 or CXCL6, we could evaluate which downstream pathways elicit pro-CSC-like characteristics in the tumor cells." (PMID 36831112, 2023). "CXCR1 and CXCR2 receptors are expressed on the surface of neutrophils, and tumor cells can secret cytokines such as CXCL1, CXCL2, and IL-8 through autocrine and paracrine, and these cytokines can bind to the corresponding receptors on the surface of neutrophils." (PMID 37373412, 2023). "As-T cells generated more IL-8 to promote tumor angiogenesis through its paracrine effect; and IL-8 receptors, C-X-C chemokine receptor type 1 (CXCR1), and CXCR2, are required for As-T cells to induce endothelial cell proliferation, migration, and tube formation, thus enhancing tumor angiogenesis." (PMID 35241635, 2022). "Considering the role played by CXCL7/CXCR1/2 in inflammatory and neoplastic diseases, the development of drugs targeting the CXCL7/CXCR1/2 axis may benefit disease treatment." (PMID 35837284, 2022). "In addition, CXCR1 and CXCR2 play an important role in the release of NETs by TANs, which in turn shield tumor cells from CD8 T cell and NK cell cytotoxicity." (PMID 35158948, 2022). "Additionally, CXCR1 and CXCR2 chemokine receptors display a high affinity for IL-8 (CXCL8), secreted by tumor cells in different cancer types." (PMID 35990652, 2022). "In addition, SX-682 (a small-molecule inhibitor of CXCR1 and CXCR2) can also inhibit the migration of MDSCs and eliminate the accumulation of MDSCs in tumor." (PMID 36225938, 2022). "Although blocking the interaction of interleukin 8 with CXCR1 and CXCR2 enhanced lapatinib-inhibited CSC activity and suppressed tumor growth in a xenograft mouse model, concern remains that targeting individual GPCRs may not be effective for eradicating CSCs." (PMID 35406489, 2022). "Furthermore, CXCR1-expressing NK cells are attracted to the TME by CXCL8 secreted by EOC cells, thus enhancing NK cell infiltration and the anti-tumor response." (PMID 35269786, 2022). "In addition, detachment stress also increased the expression of IL-8 and CXCR1 through activation of ERK and JNK signaling, which led to increased tumor growth." (PMID 35802540, 2022). "Our analysis was devoted to both receptors (CXCR1/2) and ELR+CXCL cytokines (CXCL1, 2, 3, 5, 6, 7, 8) selected from six independent datasets (M1–M6) and compared with datasets from a normal brain (NB) and a tumour brain (TB)." (PMID 36497191, 2022). "Importantly, compared with NK cells expressing only the NKG2D-specific CAR or mock control, NK cells co-expressing CXCR1 and the NKG2D CAR significantly relieved tumor burden and prolonged survival of mice carrying SKOV3 xenografts." (PMID 36428748, 2022). "For instance, IL-8 binding to the cognate receptors, namely CXCR1 and CXCR2, may promote a dysfunctional inflammatory microenvironment that contributes to tumor progression." (PMID 35954247, 2022). "Ten chemokine receptors (CXCR1, CXCR2, CXCR4, CXCR6, CCR3, CCR6, ACKR4/CCRL1, CCLR2, CX3CR1, and ACKR1/DARC) were identified as differentially expressed from the DEG analysis between Black, White and Asian patient normal and tumor samples." (PMID 35754051, 2022). "IL-8 participates in infection response and the pathogenesis of cancers by interacting with specific cell surface G protein–coupled receptors CXCR1 and CXCR2, which leads to the recruitment of neutrophils, stimulation of angiogenesis and stimulation of tumor cell proliferation." (PMID 35493517, 2022). "CXCL7 and its receptor CXCR1/CXCR2, which are aberrantly expressed in tumors, may represent new targets for clinical tumor immunotherapy." (PMID 35837284, 2022).
tumor (continued). "Overexpression of CXCR1 and CXCR2 strengthened the invasion capability of tumor cells." (PMID 35571062, 2022). "An in vitro evaluation of a clinical trial for oncolytic virotherapy with 12 patients revealed that receptor/ligand pairs C-X-C motif chemokine receptor-1 (CXCR1)/IL-8 and CC chemokine receptor 1/CC chemokine ligand 5 (CCR1/CCL5) were involved in successful migration of MSCs to the tumor." (PMID 33287630, 2021). "In addition, chemokine receptors CXCR1/2 and their ligand CXCL8 are essential for the activation and trafficking of inflammatory mediators as well as tumor progression and metastasis." (PMID 33802234, 2021). "Likewise, CXCL8/CXCR1 and CXCL8/CXCR2 axis are known to induce tumor growth, angiogenesis, motility, and EMT." (PMID 33925575, 2021). "Tumor-induced NETosis is mainly triggered by CXCR1 and CXCR2 ligands, which could be constrained by CXCR1 and CXCR2 inhibitors." (PMID 34868992, 2021). "CXCR1 and CXCR2 constitute the primary mechanism for the recruitment of neutrophils and MDSCs, which could enhance tumor progression and suppress immune therapy efficacy." (PMID 35011369, 2021). "One of the most notable CXCR1/2 ligands, IL-8 (CXCL8), is a known inducer of tumor cell plasticity, attractant of suppressive myeloid-derived suppressor cells to the tumor, and correlates with failure of treatment in numerous cancer types, including failure to checkpoint inhibitor therapy." (PMID 33669155, 2021). "Several preclinical studies have demonstrated that CAR T cells expressing chemokine receptors, including C-X-C motif chemokine receptor 1 (CXCR1), CXCR2, CCR2, CCR4, and C-C chemokine receptor type 2 (CCR2b), showed enhanced trafficking to tumor lesions and superior antitumor efficacy." (PMID 34209505, 2021). "SX-682, a CXCR1/2 inhibitor, could block tumor MDSC recruitment and enhance T cell activation and anti-tumor immunity through various forms of immunotherapy." (PMID 32391020, 2020). "Using the zebrafish model, it became clear that TANs are recruited to tumor-initiating sites through the Cxcr1-Cxcl8a pathway and that in this context, Cxcr2 is not required for efficient neutrophil recruitment." (PMID 32161595, 2020). "Furthermore, ACKR1 protein expression was localized on normal brain and tumor microvascular cells, while CXCR1 and CXCR2 were present on tumor infiltrating leukocytes." (PMID 32456359, 2020). "CXCR1 inhibition combined with chemotherapy, results in the release of CXCL8 by dying bulk (non-CSC) tumor cells and binds with CXCR1 on the surface of BCSCs." (PMID 31788042, 2019). "Moreover, the CXCR1/CXCR2 antagonist inhibited CRC liver metastasis by decreasing tumor angiogenesis and facilitating tumor cell apoptosis in a mouse model." (PMID 30691207, 2019). "Given that several αvβ6-positive tumor cell lines were found to secrete IL-8 both in vitro and when grown as xenografts in vivo, we engineered A20-28z CAR T-cells to co-express the IL-8-specific chemokine receptors, CXCR1, or CXCR2." (PMID 31091832, 2019). "As CXCL1 receptors CXCR1 and CXCR2 are expressed in both PCa cells and neutrophil, this chemokine may be a critical link in tumor microenvironment." (PMID 31500632, 2019). "Hence, we investigated the efficacy of the pharmacological antagonist of the CXCR1 and CXCR2 on 3D tumor spheroid growth and invasion." (PMID 30086759, 2018). "Furthermore, CXCL8 secreted by tumor and Treg cells has been shown to sustain MDSC migration and degranulation via CXCR1 and CXCR2 signalling to support cancer dissemination." (PMID 30591657, 2018). "Studies have shown that stimulating the neutrophil surface of CXCR1 can lead to neutrophil chemotaxis and activation, and inhibition of CXCR1 and CXCR2 can reduce the migration of neutrophils to tumor regions." (PMID 30123110, 2018).